GARNL3 (GTPase activating Rap/RanGAP domain like 3)
Synonyms: DKFZp761J1523; bA356B19.1
Tractability: PROTAC: ubiquitination databases record sites on it; its protein half-life has been measured.
Gene: Protein-coding gene on chromosome 9 (127,224,265 to 127,393,660, forward strand). Ensembl gene ENSG00000136895.
Subcellular location (Human Protein Atlas): Vesicles; Nucleoplasm
Gene Ontology:
Molecular function: GTPase activator activity
Biological process: regulation of small GTPase mediated signal transduction
Cellular component: plasma membrane
Genetic constraint (gnomAD): Loss-of-function variants: 18 observed, 49.44 expected, observed/expected ratio (o/e) 0.36, 90% interval 0.25 to 0.54. The upper end of that interval is the gene's LOEUF score, 0.54, which puts it in group 2 of 6, group 1 being the genes least tolerant of losing a copy. Missense variants: 642 observed, 839.61 expected, observed/expected ratio (o/e) 0.76, 90% interval 0.72 to 0.82. Synonymous variants: 288 observed, 320.77 expected, observed/expected ratio (o/e) 0.9, 90% interval 0.81 to 0.99.
Homologues: Orthologues: macaque GARNL3 (98% identical), chimpanzee GARNL3 (94% identical), guinea pig GARNL3 (93% identical), rabbit GARNL3 (93% identical), pig GARNL3 (92% identical), rat Garnl3 (92% identical), dog GARNL3 (92% identical), mouse Garnl3 (92% identical), tropical clawed frog garnl3 (79% identical), zebrafish garnl3 (73% identical), Drosophila melanogaster RapGAP1 (16% identical), Caenorhabditis elegans F53A10.2 (15% identical). Paralogues in human: SIPA1L2 (26% identical), SIPA1L3 (25% identical), SIPA1L1 (25% identical), SIPA1 (21% identical), RAP1GAP2 (18% identical), RAP1GAP (17% identical).
Diseases named in the same sentence as GARNL3 in open-access papers:
GARNL3 is named in the same sentence as 3 diseases in open-access papers, as found by Europe PMC text mining. Sharing a sentence is not in itself a finding about the gene and the disease. The quoted sentences say what the papers report.
autism (1 paper, 2021). Persistent deficits in social interaction and communication and interaction as well as a markedly restricted repertoire of activity and interest as well as repetitive patterns of behavior. "Alternatively, spliced isoforms of NAPB are associated with autism, and GARNL3 is linked with intellectual disability." (PMID 33423377, 2021).
GARNL3 also shares sentences with these, for which no sentence is quoted: epilepsy (1 paper); Intellectual disability (1).